ABCB4 (ATP binding cassette subfamily B member 4)
Diseases named in the same sentence as ABCB4 in open-access papers (continued):
Sharing a sentence is not in itself a finding about the gene and the disease.
liver disease (continued). "This differential role of TLR4 might be due to interaction with the pre-existing liver disease (ABCB4 deficiency)." (PMID 27391331, 2016). "Progressive Familial Intrahepatic Cholestasis Type 3 (PFIC3) is a rare inherited liver disease caused by a mutation in the ABCB4 gene, leading to dysfunction of multidrug resistance protein 3 (MDR3)." (PMID 40200381, 2025). "As previously noted, it is well established that heterozygous variants in ABCB4 and ABCB11 can result in milder forms or late-onset liver disease in adults." (PMID 40870862, 2025). "While heterozygous carriers of ABCB4 are prone to develop liver disease, the role of heterozygous NBAS is not well known." (PMID 40870862, 2025). "Mutations in the bile salt export pump (BSEP, ABCB11) the multidrug resistance protein 3 (MDR3, ABCB4) cause progressive familial intrahepatic cholestasis (PFIC) types II and III, respectively (severe cholestatic liver diseases appearing in early infancy)." (PMID 31597297, 2019). "In conclusion, the results presented in this work pave the way for future investigations on the molecular mechanisms underlying the canalicular membrane localization of ABCB4, which will guide the development of new therapeutic strategies for patients with liver diseases related to ABCB4 defects." (PMID 35203270, 2022). "Therefore, the downregulation of Cyp8b1 in the ACLI model might trigger harmful consequences during liver disease progression, further increasing the known risk of HCC in Abcb4−/− mice." (PMID 34360670, 2021). "Furthermore, the c.834-66G>T variant of ABCB4 was significantly less frequent in CF patients with liver disease as compared to those with no liver disease." (PMID 24222913, 2013). "Here we show that, in PSC patients, ABCB11 and ABCB4 are significantly overexpressed when compared to other cholestatic and noncholestatic liver diseases." (PMID 31886153, 2019). "Increased ALT activity in Abcb4−/−/HBsAg+/− mice nearly reflects the sum of individual ALT levels in corresponding transgenic/knock out controls and thus suggests an additive effect of both liver diseases." (PMID 28881751, 2017). "It is caused by pathogenic variants of the ATP binding cassette subfamily B member 4 (ABCB4) gene and usually progresses from chronic cholestasis with or without jaundice to portal hypertension and end-stage liver disease within the first to second decade of life." (PMID 36330364, 2022). "The aim of this study was to investigate the expression and localization of the critical bile transporters ABCB11 and ABCB4 in liver tissue samples from patients with different types of chronic cholestatic and noncholestatic liver disease, with particular emphasis on PSC." (PMID 31886153, 2019). "Mice deficient in the PC-floppase ABCB4 (mdr2 knock-out mice) do not fully develop PFIC type 3 because of the reduced toxicity of the rodent bile acid pool, but they do develop cholelithiasis and inflammatory liver disease most similar to Sclerosing Cholangitis (SC)." (PMID 28220208, 2017). "Therefore, ABCB11 and ABCB4 expressions were investigated on formalin-fixed and paraffin-embedded (FFPE) material in a patient cohort of total 43 patients with or without cholestatic liver diseases, on protein level using immunohistochemistry and on RNA level using nanoString technology." (PMID 31886153, 2019).
sclerosing cholangitis (44 papers, 2007 to 2025). A chronic, autoimmune inflammatory liver disorder characterized by narrowing and scarring of the lumen of the bile ducts. "In contrast, in Mdr2 (Abcb4) deficient mice with sclerosing cholangitis, a low dose of IL-2 treatment diminishes biliary injury and fibrosis by the expansion of intrahepatic Tregs." (PMID 32676074, 2020). "Population genetic studies have also linked ABCB4 variants to the development of inflammatory cholangiopathies, sclerosing cholangitis, and cirrhosis that are already considered to predispose to cholangiocarcinoma." (PMID 28220208, 2017). "It has been suggested recently that genetic variants of ABCB11 and ABCB4 could be involved in the pathogenesis of primary sclerosing cholangitis (PSC)." (PMID 31886153, 2019). "It is unclear whether other acquired human cholestatic liver diseases such as primary sclerosing cholangitis (PSC) or primary biliary cholangitis (PBC) are linked to ABCB4 mutations, but mice with Abcb4 impairment do spontaneously develop sclerosing cholangitis with features resembling human PSC." (PMID 36733378, 2022). "Second, we evaluated the MDR2-KO mouse, which spontaneously exhibits primary sclerosing cholangitis (PSC), a chronic liver disease; with targeted disruption of the multi-drug resistance gene 2 (Abcb4)." (PMID 36071089, 2022). "ABCB4 is well known to show mutations in patients with progressive familial intrahepatic cholestasis (PFIC3), but there are also reports of association with cholestatic diseases such as primary sclerosing cholangitis (PSC) and PBC." (PMID 41180305, 2025). "Abcb4-/- mice spontaneously develop sclerosing cholangitis, which resembles human PSC." (PMID 37307826, 2024). "Here, we aimed to explore the potential of cilofexor (GS-9674), a non-steroidal FXR agonist, as a therapeutic approach for counteracting features of cholestatic liver injury by evaluating its efficacy and mechanisms in the Mdr2/Abcb4 knockout (-/-) mouse model of sclerosing cholangitis." (PMID 37841639, 2023). "In the present study we investigated whether treatment with the GLP-2 analogue teduglutide improves liver injury in the Mdr2/Abcb4-/- mouse model of sclerosing cholangitis possibly via activation of NR4a1/Nur77 in HSCs." (PMID 37572734, 2023). "Abcb4−/− mice are widely used as a model of sclerosing cholangitis." (PMID 39130146, 2023). "Adenosine triphosphate-binding cassette subfamily B member 4 (Abcb4)−/− (ie, Mdr2: multiple drug resistance 2) mice are used as a model for sclerosing cholangitis because they reflect the progressive fibrosing cholangitis aspects of human PSC and also develop intrahepatic cholangiocarcinoma." (PMID 39130146, 2023). "Thus, Abcb4−/− mice are widely used as a model for sclerosing cholangitis." (PMID 36866272, 2023). "Thus, we aimed to test whether application of the GLP-2 analogue teduglutide has hepatoprotective and antifibrotic effects in the Mdr2/Abcb4-/- mouse model of sclerosing cholangitis displaying hepatic inflammation and fibrosis." (PMID 37572734, 2023). "As a recent study reported that Mdr2 KO mice develop liver lesions mimicking sclerosing cholangitis characterized by biliary strictures and dilatations, we also looked for ABCB4 gene mutations and sequence diversity in 34 consecutive patients with primary sclerosing cholangitis." (PMID 17562004, 2007). "However, the therapeutic use of UDCA is no significant reduced CD11b and F4/80 in sclerosing cholangitis in Mdr2 (Abcb4) knockout mice." (PMID 30884843, 2019).
progressive familial intrahepatic cholestasis type 3 (40 papers, 2009 to 2026). "Biallelic pathogenic variants of ABCB4 result in progressive familial intrahepatic cholestasis 3, an autosomal recessive disorder." (PMID 40870862, 2025). "Progressive familial intrahepatic cholestasis type 3 (PFIC3) is a rare cholestatic liver disease with autosomal recessive inheritance caused by mutations in the ABCB4 gene." (PMID 37575491, 2023). "ABCB4 mutation indicated the probability of progressive familial intrahepatic cholestasis-type 3 (PFIC3)." (PMID 32382272, 2020). "Progressive familial intrahepatic cholestasis type 3 (PFIC3) is a rare monogenic disease caused by mutations in the ABCB4 gene, resulting in a reduction in biliary phosphatidylcholine." (PMID 31836711, 2019). "Mutations in the ABCB4 gene result in progressive familial intrahepatic cholestasis type 3, intrahepatic cholestasis of pregnancy, low-phospholipid-associated cholelithiasis, primary biliary cirrhosis, and cholangiocarcinoma." (PMID 25133187, 2014). "Cholestatic liver diseases related to ABCB4 variants include progressive familial intrahepatic cholestasis type 3 (PFIC3), benign recurrent intrahepatic cholestasis, intrahepatic cholestasis of pregnancy (ICP), drug-induced liver injury (DILI), and low phospholipid associated cholelithiasis (LPAC)." (PMID 38610052, 2024). "These include ABCA1 (HDL-deficiency, Tangier disease), ABCB4 (progressive familial intrahepatic cholestasis type 3; PFIC3), ABCB11 (PFIC2), ABCC2 (Dubin-Johnson syndrome), ABCC6 (pseudoxanthoma elasticum, general arterial calcification of infancy) and ABCG2 (gout)." (PMID 24316454, 2014). "Rare genetic hepatobiliary diseases, such as PFIC2 (ABCB11/BSEP deficiency) and progressive familial intrahepatic cholestasis type 3 (PFIC3) (ABCB4/MDR3 deficiency) highlight the importance of apposite BA handling in maintaining both liver and biliary health." (PMID 40513781, 2025). "ABCB4 gene causing progressive familial intrahepatic cholestasis type 3 (PFIC3) with high gamma-glutamyl transferase (GGT) was the most common gene (14 children/13 variants)." (PMID 41165782, 2025). "Mutations in the ABCB4 gene are associated with conditions such as progressive familial intrahepatic cholestasis type 3 (PFIC3) and intrahepatic cholestasis of pregnancy." (PMID 39770445, 2024). "Progressive familial intrahepatic cholestasis type 3 (PFIC3), an inherited juvenile-onset, rare hereditary cholestatic disorder, is caused by homozygous mutation in the ATP binding cassette subfamily B member 4 (ABCB4) gene." (PMID 32204422, 2020). "ABCB4 deficiency, due to genetic variations, is responsible for progressive familial intrahepatic cholestasis type 3 (PFIC3) and other rare biliary diseases." (PMID 31040306, 2019). "Human ABCB4 mutations result in a wide spectrum of phenotypes, ranging from progressive familial intrahepatic cholestasis type 3 (PFIC3) to adult cholestatic liver disorders." (PMID 25133187, 2014). "In agreement with these proposed roles, ABCB4 mutations result in a broad spectrum of phenotypes ranging from progressive familial intrahepatic cholestasis type 3 (PFIC3) to ABCB4-related cholestatic liver disorders of varying manifestation and severity in adults." (PMID 36901890, 2023). "Variations in the ABCB4 gene give rise to several biliary diseases, including progressive familial intrahepatic cholestasis type 3 (PFIC3), an autosomal recessive disease that can be lethal in the absence of liver transplantation." (PMID 36674751, 2023). "Variations in the ABCB4 gene are associated with several rare cholestatic diseases, including Progressive Familial Intrahepatic Cholestasis type 3 (PFIC3), Low Phospholipid-Associated Cholelithiasis (LPAC) syndrome, and Intrahepatic Cholestasis of Pregnancy (ICP)." (PMID 34209301, 2021).
progressive familial intrahepatic cholestasis type 3 (continued). "Pathogenic mutations in the ABCB4 gene sequence are associated with rare biliary diseases, in particular progressive familial intrahepatic cholestasis type 3 (PFIC3), which develops early in childhood and may be lethal in the absence of liver transplantation." (PMID 26789121, 2016). "It has been recognized that ABCB4 deficiency caused by genetic mutations or variations mainly involves three major hepatobiliary diseases: progressive familial intrahepatic cholestasis type 3 (PFIC3), intrahepatic cholestasis of pregnancy (ICP), and low phospholipid-associated cholelithiasis (LPAC)." (PMID 35741809, 2022). "Progressive familial intrahepatic cholestasis Type 3 (PFIC3) is a rare, autosomal recessive, and hepatocellular-originating cholestatic liver disease caused by mutations in the ABCB4 gene, which encodes the multidrug resistance protein 3 (MDR3)." (PMID 39872042, 2025). "Progressive familial intrahepatic cholestasis type 3 (PFIC3, OMIM#602347) which results from biallelic pathogenic variations in ABCB4 constitutes the most severe phenotype related to MDR3 deficiency." (PMID 37701337, 2023). "Human MDR3 (ABCB4) mutations result in a wide spectrum of phenotypes, ranging from progressive familial intrahepatic cholestasis type 3 (PFIC3) to adult cholestatic liver disorders." (PMID 29420298, 2018). "Dysfunction of ABCB4 can lead to a range of clinical phenotypes ranging from slightly increased liver function tests, to gallstone disease, intrahepatic cholestasis of pregnancy (ICP), progressive familial intrahepatic cholestasis type 3 (PFIC-3), and biliary cirrhosis." (PMID 36397154, 2022).
intrahepatic cholestasis (33 papers, 2007 to 2025). A cholestasis characterized by impairment of the bile flow caused by obstruction located in the liver. "55.6% of participants with rare heterozygous ABCB4/ABCB11 variants or a history of intrahepatic cholestasis of pregnancy showed evidence of liver involvement, highlighting the utility of genetic screening and monitoring." (PMID 41436587, 2025). "In terms of pure intrahepatic cholestasis with recurrent gallbladder stones, PFIC-3 due to ABCB4 mutation should be considered until whole exome sequencing are available." (PMID 40184140, 2025). "After excluding other causes of abnormal liver function and intrahepatic cholestasis, genetic testing led to the diagnosis of heterozygous mutations in the ABCB4 gene causing PFIC3." (PMID 37488596, 2023). "Disease-specific ABCB4 gene polymorphisms have been described in some intrahepatic cholestasis diseases, suggesting decreased MDR3 expression and function." (PMID 36569137, 2022). "ABCB4 c.711A > T (rs2109505) has been linked to intrahepatic cholestasis of pregnancy, low phospholipid-associated cholelithiasis and elevated liver serum biomarkers (ALT, AST, GGT)." (PMID 36397154, 2022). "ABCB4 gene encodes the multidrug resistant protein 3 (MDR3) and its mutations induce PFIC3 as well as intrahepatic cholestasis of pregnancy (ICP) and drug‐induced liver injury (DILI)." (PMID 31568708, 2019). "As a transporter, ABCB4 gene encodes the MDR3 protein which has a specific physiological function with intrahepatic cholestasis as a phosphatidylcholine carrier and transports only specific compounds." (PMID 27203216, 2016). "Recently, mutations of ABCB4 were reported in early-onset gallstone disease, cholestasis of pregnancy, liver cirrhosis, and hepatobiliary cancer." (PMID 27203216, 2016). "In humans, ABCB4 associates with progressive familial intrahepatic cholestasis, and intrahepatic cholestasis during pregnancy is a common disorder associated with fetal AF." (PMID 25888430, 2015). "This has been confirmed through diseases such as intrahepatic cholestasis and Dubin-Johnson syndrome caused by mutations in ABCB4 and ABCC2, respectively." (PMID 24732756, 2014). "Histopathologic findings associated with ABCB4 associated diseases in people, including intrahepatic cholestasis, cholecystitis, and periportal inflammation, are not commonly reported in dogs with gall bladder mucoceles." (PMID 20598156, 2010). "Additionally, ABCB4 variants elevate the risk of drug-induced intrahepatic cholestasis, gallstone disease, gallbladder and bile duct carcinoma, liver cirrhosis and abnormal liver function tests." (PMID 39262913, 2024). "In this study, we present the case of a 19-year-old Chinese female patient with a novel mutation in ABCB4 who experienced intrahepatic cholestasis of unknown etiology 2 years before." (PMID 32321542, 2020). "The onset of symptoms typical for LPAC syndrome have been reported at the end of or following pregnancy (56% of women with early onset of symptoms and ABCB4 mutations presented also with an history of intrahepatic cholestasis of pregnancy and 14% had fetal complications)." (PMID 17562004, 2007). "Cases were defined as participants with rare (minor allele frequency <1%) heterozygous loss of function (LoF) variants in ABCB4 and ABCB11 (genotype re-call) or with a previous intrahepatic cholestasis of pregnancy (ICP) diagnosis (ICD10 O26.6)." (PMID 41436587, 2025). "ABCB4 deficiency is associated with a variety of hepatobiliary disorders in people including progressive familial intrahepatic cholestasis (PFIC type 3), cholelithiasis, and cholestasis of pregnancy." (PMID 20598156, 2010).